INS (insulin)
Diseases named in the same sentence as INS in open-access papers (continued):
Sharing a sentence is not in itself a finding about the gene and the disease.
Insulin resistance (continued). "We therefore believe that, in conditions of insulin resistance and hyperinsulinemia, prolonged exposure to high insulin might induce not only β-cell insulin resistance, but also resistance to IGF-1, which could contribute to β-cell failure in T2D." (PMID 32150819, 2020). "Moreover, insulin resistance is a frequent condition in obese patients, and an intense cross-talk between insulin and estrogen signaling pathways has already been demonstrated." (PMID 33109233, 2020). "Although Type 1 diabetes is not brought on by obesity, people with Type 1 diabetes can develop obesity and insulin resistance as a result of long term insulin therapy, which could require combination therapies for treatment." (PMID 32150819, 2020). "Visceral fat and insulin resistance are closely connected, so differences in insulin improvement could be mediated by different body compositions." (PMID 32916989, 2020). "Furthermore, LPS administration to mice and healthy humans results in systemic and adipose tissue inflammation and insulin resistance, confirming that LPS affects insulin sensitivity." (PMID 32984066, 2020). "However, the inverse associations between starch intake and insulin and HOMA-IR were stronger in males and with similar effect sizes for all AMY1 CNV groups, possibly because males have higher rates of insulin resistance than females." (PMID 33490099, 2020). "In addition, we demonstrated that curcumin supplementation positively affects glycaemic control via reduction in insulin resistance and fasting serum insulin compared with the placebo group." (PMID 32283762, 2020). "Metformin may have a small effect reducing insulin resistance, but its main effect is to keep the liver from sending out too much insulin and over-compensating when blood glucose is a little low, like when it helps to prevent the dawn effect." (PMID 32602843, 2020). "Many alterations in insulin associated mechanisms in the kidney are driven by insulin resistance (IR), leading to diabetic nephropathy if not reestablished." (PMID 32850773, 2020). "Similarly, p70 S6K, the downstream effector of mTOR, is implicated in the serine phosphorylation of IRS-1, leading to impaired insulin signaling and insulin resistance." (PMID 32664532, 2020). "Intramyocellular lipid (IMCL) content associates with development of insulin resistance, albeit not in insulin-sensitive endurance-trained athletes (trained)." (PMID 32880685, 2020). "The hypothesis states that common genetic factors that either increase insulin resistance or reduce insulin secretion may lead to both reduced birth weight and disease in later life." (PMID 33490284, 2020). "Thus, AN1284 reversed renal insulin resistance by decreasing the direct effect of insulin on podocytes or tubular cells, which express all elements of the insulin-signaling cascade." (PMID 32218769, 2020). "Given that ASC acquire insulin sensitivity during differentiation, a decline in their adipogenic potential might drive insulin resistance by limiting adipose tissue expansion." (PMID 32244726, 2020). "In one animal study, encapsulated Propolis could improve insulin resistance in diabetic rats with increase insulin sensitivity mechanism." (PMID 32817750, 2020). "In addition, SHR-Glo1+/− rats exhibited amelioration of insulin resistance in adipose tissue when insulin-stimulated glucose incorporation into lipids (lipogenesis) was significantly higher." (PMID 33255888, 2020). "Free fatty acids (FFAs) potentially derived from elevated TGs might decrease insulin sensitivity, creating a vicious cycle between TG levels and insulin resistance." (PMID 32377519, 2020). "Pesticides induce insulin resistance by acting on insulin signaling pathways." (PMID 33371482, 2020). "Involvement of this novel interactor in insulin signalling and podocyte biology may explain how insulin resistance alters morphology and integrity of the glomerular filtration barrier." (PMID 33458251, 2020).
Insulin resistance (continued). "In T2DM, the response to insulin is diminished, and this is defined as insulin resistance." (PMID 32825758, 2020). "Hyperinsulinemia (elevated insulin levels) and insulin resistance are apparently the link." (PMID 32983729, 2020). "Insulin resistance can promote arterial stiffness and plaque progression through downregulation of insulin signaling pathways and alterations in lipid metabolism; moreover, inflammatory pathways support the role of insulin resistance in the pathophysiology of aortic stiffness." (PMID 31965377, 2020). "Moreover, a FMD in diabetic (i.e., db/db) mice confers improvements in β-cell function as indicated by decreased plasma glucose and increased plasma insulin levels, as well as a reduction in insulin resistance." (PMID 33193730, 2020). "Given the body weight and fat mass reducing effects of thylakoid supplementation in our study, it is expected that thylakoid intake could improve insulin sensitivity and alleviate insulin resistance, as has been demonstrated in other studies." (PMID 32782010, 2020). "Consumption of fructose and all-natural sweeteners but not corn syrup were associated with lower insulin resistance as revealed by reduced fasting insulin and homeostatic model assessment of insulin resistance (HOMA-IR) compared to sucrose treatment of HFHS-fed rats." (PMID 32751772, 2020). "Muscle-specific transgenic overexpression of Pgc-1α contributed to the development of diet-induced insulin resistance, probably due to an increase in FA and reduced glucose uptake, inducing intramuscular lipid accumulations and then the alteration of insulin signaling." (PMID 33348802, 2020). "The present study demonstrates commonalities between metabolites and genetic variants associated with insulin sensitivity in the gravid and non-gravid states and provides insights into mechanisms underlying pregnancy-induced insulin resistance." (PMID 32556615, 2020). "Taken together, these results indicate that higher U-NM concentrations are significantly associated with increased insulin resistance, but not decreased insulin secretion, in a general Japanese population." (PMID 32053635, 2020). "Glucose tolerance tests with corresponding insulin measurements and subsequent insulin resistance index (IRI) calculations were performed to quantify the functional metabolic effects of the treatment-induced alterations in BM (IRI = Glucose AUC × Insulin AUC/100)." (PMID 32587574, 2020). "There are, however, studies using a HFD to induce insulin resistance in mice that have reported a decrease in resting and insulin-stimulated soleus muscle mitochondrial respiration and decreased mitochondrial respiration and ADP sensitivity across a range of biologically relevant ADP concentrations." (PMID 32971810, 2020). "Insulin resistance is strongly associated with nutrient overload (such as elevated levels of free fatty acids (FFA), glucose and/or amino acids), cellular stress, inflammation and high levels of circulating insulin, known as hyperinsulinemia." (PMID 32230718, 2020). "Type-2 diabetes is linked to obesity and genetic predisposition, where insulin secretion fails to compensate for insulin resistance." (PMID 32117058, 2020). "TNF-α has been found to promote insulin resistance and disrupt insulin signaling." (PMID 32905192, 2020). "However, beta-cell mass in subjects with obesity is assumed to increase, since plasma insulin levels in obese subjects increase to compensate for insulin resistance, a process known as hyperinsulinemia." (PMID 33339276, 2020). "However, it also had been found that in mice, p-IRS-1S307 (human S312) positively regulated the severity of insulin resistance by maintaining proximal insulin signaling." (PMID 33344443, 2020). "However, there is little information about the differences in intestinal insulin signalling pathways between subjects with low and high insulin resistance." (PMID 31936857, 2020).
Insulin resistance (continued). "Amongst obese women for example, excessive insulin resistance is considered to be the predominant pathophysiological mechanism, whereas insulin secretory defects may predominate in lean women with GDM." (PMID 32240196, 2020). "Conversely, in the EH population, however, we believe that decreased insulin sensitivity or increased insulin resistance may mainly contribute to hyperglycemia and/or DM and to MetS." (PMID 33101195, 2020). "A comprehensive understanding of the pathogenesis involved in insulin resistance may enable the identification of targets for improving insulin sensitivity as well as preventing and treating Type 2 diabetes (T2D)." (PMID 32911464, 2020). "Insulin resistance can hence be attributed to a decrease in insulin responsiveness (a downward shift of the insulin dose–response curve), a decrease in insulin sensitivity (a rightward shift of the insulin dose–response curve), or a combination of both." (PMID 32823892, 2020). "Furthermore, VAT/m3 was found to be a significantly better determinant of insulin resistance or prediabetes than uncorrected VAT volume (p < 0.001/0.019 for females/males regarding insulin sensitivity, p < 0.001/< 0.001 for females/males regarding HbA1c)." (PMID 32664590, 2020). "T2D is due to insulin resistance, an impaired response of the body to insulin despite hyperinsulinemia, as well as the failure of the pancreas to secrete adequate insulin for glucose homeostasis." (PMID 31871214, 2020). "Our study suggests that only those with preoperatively beta-cells with remaining capacity to produce enough insulin when needed may normalize the metabolic control after improvement of hepatic insulin resistance." (PMID 32934313, 2020). "In contrast, in type 2 diabetes, obesity-related insulin resistance may result in elevated levels of insulin and C-peptide." (PMID 32528556, 2020). "The reduced activity of Akt following insulin stimulation was associated with increased expression of serine 307 phosphorylation of the IRS1, a residue phosphorylation known to be related to insulin resistance." (PMID 33303821, 2020). "So, a prospective and longer follow-up of women with previous GDM in larger population, and the test for serum C-peptide level is needed in order to better explore the transition of insulin resistance and insulin secretion postpartum, and to elaborate the mechanisms of transition from GDM to T2DM." (PMID 32184821, 2020). "In conclusion, higher U-NM levels within the physiologic range are significantly associated with insulin resistance, but not with insulin secretion, in a general Japanese population." (PMID 32053635, 2020). "Oxidative stress may also lead to insulin resistance due to insulin signalling impairment, which can be restored through honey treatment." (PMID 33299532, 2020). "Furthermore, we observed that insulin, insulin resistance, and C-reactive protein (CRP) were lower during egg intake compared to baseline, an effect not seen with the choline supplement." (PMID 33066009, 2020). "The development of insulin resistance in aged Cdk1 cKO mice is supported by our observation of reduced insulin signaling, increased blood glucose levels, reduced glucose tolerance, and diminished response to insulin." (PMID 33345777, 2020). "The exposure of the liver to such large quantities of fructose leads to rapid stimulation of lipogenesis and triglycerides accumulation, which in turn contributes to reduced insulin sensitivity and hepatic insulin resistance/glucose intolerance, leading to an increase of circulating insulin." (PMID 32521542, 2020). "Genes on mouse Chr 11 could explain glucose intolerance, impaired insulin secretion, insulin resistance in NSY mice under sucrose administration." (PMID 32703163, 2020). "Glucose intolerance is due to impaired insulin secretion and/or increased insulin resistance." (PMID 33324347, 2020). "Diabetes is a disease, in which dysregulation of insulin signaling leads to insulin resistance." (PMID 32375323, 2020).
Insulin resistance (continued). "Obesity could stimulate the formation of lipid metabolites, hormones, and cytokines, which involves changes in the insulin signaling pathway and the accelerated progression of insulin resistance." (PMID 32714368, 2020). "Insulin resistance (when cells do not respond to insulin) occurs in T2D, is associated to increased dementia risk, partly due to poor insulin signaling in neurons." (PMID 32265637, 2020). "Insulin resistance in β-cells can result in a decrease in insulin secretion." (PMID 32774144, 2020). "In fact, it can be stated that the increase in the plasma level of apelin is a compensatory mechanism activated during insulin resistance because it has been found to increase the glucose uptake in the skeletal muscle and AT and repress lipolysis in healthy and insulin‐resistant rats." (PMID 33278072, 2020). "Leptin may promote atherogenesis processes and insulin resistance and on the other hand, it may exert antiatherogenic effect and increase insulin sensitivity." (PMID 33198735, 2020). "The significant differences observed between the WT and KO mice with respect to the insulin tolerance test also suggest that P2Y2 receptor may likely to play a significant role in promoting insulin resistance." (PMID 32582029, 2020). "Insulin resistance is a condition defined by a reduced response to insulin in target tissues." (PMID 32393179, 2020). "In humans, negative associations between free thyroxine and insulin sensitivity suggest a potential role for thyroid hormone signalling in the development of insulin resistance." (PMID 31968625, 2020). "This apparent duality was exemplified by the observation of a cohort specific positive or negative association with markers of insulin resistance in overweight insulin resistant males." (PMID 33198235, 2020). "The evidences for alterations in insulin sensitivity found in the present trial are reinforced by significant increases in lactate concentrations over time of study, since such increase is considered a main biomarker of obesity and insulin resistance." (PMID 32932852, 2020). "However, as the disease progresses, β-cells fail to secrete sufficient insulin to compensate for insulin resistance." (PMID 32079203, 2020). "Diabetic patients showed meaningful reductions in fasting glucose (−35.22 mg/dL; p < 0.01), fasting insulin (−4.55 microunits/mL; p < 0.01), hemoglobin A1c (−0.79%; p = 0.02), and insulin resistance (homeostatic model assessment—insulin resistance; −2.25; p < 0.01)." (PMID 33053864, 2020). "In T2D patients, chronic low-grade inflammation and oxidative stress over time may impair insulin signaling and may induce a state of insulin resistance, marked by hyperglycemia." (PMID 32806763, 2020). "Insulin resistance is hypothesised to be responsible for the failure of insulin to control fasting glucose, and insulin resistance is measured as the inability of insulin to control fasting glucose." (PMID 33365205, 2020). "The NWO group had the higher mean serum levels of insulin (9.02 ± 4.75 vs. 6.24 ± 2.51, P = 0.009), leptin (17.31 ± 8.10 vs. 9.94 ± 4.30, P < 0.001) and homeostatic model assessment of insulin resistance (HOMA-IR) (33.77 ± 20.71 vs. 23.48 ± 10.03, P = 0.009) compared to the NWNO group." (PMID 33198735, 2020). "Recently, insulin resistance, characterized by a decreased cellular response to insulin, was shown to have a significant impact on various adverse clinical outcomes, including hypertension, diabetes mellitus, nonalcoholic fatty liver disease, cardiovascular diseases, and even kidney diseases." (PMID 32546151, 2020). "Although physiological levels of Se may exert an insulin-mimetic effect, supraphysiological high doses of Se are reported to impair insulin synthesis and induce insulin resistance in different species." (PMID 32344656, 2020).
Insulin resistance (continued). "At present, we observed that incubation with palmitate-induced insulin resistance by attenuating insulin-stimulated glucose uptake, the phosphorylation of IRS1 and AKT, and the distribution of GLUT4, but trilobatin prohibited these effects of palmitate in C2C12 myotubes in a dose-dependent manner." (PMID 33062046, 2020). "Indeed, in 1996, Hotamisligil demonstrated that inflammatory cytokines interfere with insulin signaling, inducing insulin resistance." (PMID 32604771, 2020). "To further study the optimum way of oral vitamin D administration, we conducted subgroup analysis revealing that daily intake could reduce serum glucose and insulin level, while low-dose intake could alleviate insulin resistance conditions." (PMID 33424968, 2020). "Furthermore, both forms of inulin, compared with cellulose, reduced HOMA-IR, adipose tissue insulin resistance, and fasting insulin, and increased the Matsuda insulin sensitivity index." (PMID 32210176, 2020). "Due to the role of insulin in establishing glucose homeostasis and altering vascular tone, we hypothesise that high insulin levels, secondary to acute insulin resistance, are the mechanism of action responsible for the increase in bAPV." (PMID 31953778, 2020). "Whole body insulin resistance (IR) reflects defective insulin action in tissues such as muscle, liver, adipose tissue, gut and brain, which may precede the development of cardiometabolic diseases." (PMID 32122428, 2020). "Further detrimental actions of insulin during insulin resistance are the promotion of calcium ion influx into smooth vascular cells favoring contractility/vascular stiffening and the enhanced sodium reabsorption in renal tubules increasing the risk of hypertension." (PMID 32819363, 2020). "Moreover, both lipid atrophy and HGHI exposure induced insulin resistance as demonstrated by a significant reduction on P-Akt/Akt signaling in these cells after 10 min stimulation with insulin." (PMID 32214011, 2020). "Mechanistically, mitochondrial overload might generate by-products, which would affect the insulin signaling pathway, thus leading to insulin resistance." (PMID 33168096, 2020). "Chronic hyperinsulinemia can lead to insulin resistance in patients, hence we wondered whether plasma insulin remained high in Cdk1 cKO mice over time." (PMID 33345777, 2020). "Additionally, high levels of 5-HT modulate glucose metabolism, enhancing pancreatic insulin secretion, which gives rise to insulin resistance that promotes hepatic steatosis." (PMID 33081272, 2020). "In addition to contributing to chronic low-grade systemic inflammation, adipose-tissue-derived cytokines are also reported to induce systemic insulin resistance, by impeding downstream insulin signaling." (PMID 33343375, 2020). "To determine whether this systemic insulin resistance could be correlated with altered adipose insulin signaling pathway, we measured the phosphorylation of AKT in response to insulin as a read-out of insulin signaling." (PMID 33324235, 2020). "Some researchers, including our group, have suggested that in conditions of insulin resistance and hyperinsulinemia, prolonged exposure to high concentrations of insulin may induce insulin resistance in β-cells and negatively impact their function and mass." (PMID 32150819, 2020). "This could be attributed to patients with comorbid HIV and DM developing a greater degree of insulin resistance, as both conditions progress, and therefore require higher doses of insulin to achieve glycaemic control with a propensity for hypokalaemia." (PMID 32832115, 2020). "Type 2 diabetes mellitus refers to a chronic metabolic disease characterized by upregulated blood glucose level and accompanied by symptoms (e.g., insulin resistance, insufficient insulin secretion, and disorders of lipid metabolism), posing serious threats to human health." (PMID 33456489, 2020).